BCL2 (BCL2 apoptosis regulator)
Diseases named in the same sentence as BCL2 in open-access papers (continued):
Sharing a sentence is not in itself a finding about the gene and the disease.
lymphoma (continued). "One of the strategies to avoid acquired resistance and to increase the clearance of malignant lymphocytes is the combinations of PI3K inhibitors with other anti-lymphoma agents, including anti-CD20 antibodies, BTK inhibitors, or BCL2 inhibitors." (PMID 32197371, 2020). "DEL is defined as positivity of both MYC and BCL2 in lymphoma tissues by IHC (Cut-off values: 40–50% for MYC, 50–70% for BCL2)." (PMID 32664092, 2020). "The ‘DH’ lymphomas are defined as a chromosomal breakpoint affecting the MYC/8q24 and another recurrent genetic abnormality, mainly involving BCL2, BCL6, BCL3 or other genes." (PMID 32459397, 2020). "Even though BCL-2 is overexpressed in all FL cases, the ORR and CR rates in this lymphoma subtype were only 38% and 14%, respectively." (PMID 32290241, 2020). "FL can also transform into a composite lymphoma, combining a HGBL with BCL2 and/or BCL6 and MYC rearrangements, and a B-ALL characterized by a loss of maturity markers, such as CD20 and surface immunoglobulins." (PMID 32713346, 2020). "High-grade B-cell lymphomas with MYC and BCL2 and/or BCL6 rearrangements represent a quite recently defined entity of lymphoma with aggressive nature, high genomic complexity and poor prognosis." (PMID 33339535, 2020). "Specific oncogenes, such as MYC, BCL-2, and BCL-6, converge proliferation, differentiation, and anti-apoptotic signaling in lymphoma cells and play critical roles in lymphomas." (PMID 32296035, 2020). "In addition, 20–35% of DLBCL cases show co-expression of MYC and BCL2 by immunohistochemistry in the absence of chromosomal translocations, which represent “double expressor” lymphomas (DEL) also associated with poor clinical outcome, but are mainly of the ABC subtype." (PMID 33260693, 2020). "High-grade B-cell lymphoma, with MYC and BCL2 and/or BCL6 translocations (so called “double-hit” or “triple-hit” lymphomas in the WHO 2008) often show complex karyotypes." (PMID 30696948, 2019). "BET-PROTACs have shown synergistic interactions with bcl-2 and CDK4/6 inhibitors in lymphoma probably through the activation of compensatory pathways." (PMID 31470872, 2019). "Among the 51 cases with MYC/BCL2 co-expression, 14 cases showed concurrence of MYC, BCL2 and/or BCL6 genetic abnormalities, and the remaining 37 cases were classified as double-expressor lymphoma (DEL)." (PMID 31315646, 2019). "In terms of further histological/molecular features of DLBCL, one patient with clonally related lymphoma was a double expressor of MYC and BCL2, and one presented with CD5+ aggressive lymphoma following an initially CD5− MALT lymphoma." (PMID 31124124, 2019). "Double/triple-hit lymphomas (DHL/THL) account for 5–10% of diffuse large B cell lymphoma (DLBCL) with rearrangement of MYC and BCL2 and/or BCL6 resulting in MYC overexpression." (PMID 31288832, 2019). "In the most recent WHO revision of lymphoma classification, DHL/THL category is now recognized as "high-grade B cell lymphoma (HGBL) with rearrangements of MYC and BCL-2 and/or BCL-6." (PMID 31288832, 2019). "“Double hit” lymphomas are characterized by the presence of both MYC and BCL-2 (or less commonly BCL-6) rearrangements, while “triple-hit” lymphomas demonstrate MYC, BCL-2, and BCL-6 rearrangements." (PMID 31115699, 2019). "Triple hit lymphomas harbor MYC, BCL-2, and BCL-6 rearrangements and have an aggressive clinical course and poor prognosis." (PMID 30718665, 2019). "Recently, a new distinct entity with poor prognosis was described as “the double/triple hit lymphomas”, with rearrangements of MYC and BCL-2 and/or BCL-6." (PMID 31740676, 2019). "Here we demonstrate that targeting Bcl-2 with the more selective inhibitor, ABT-199, is sufficient to synergize with eIF4A inhibition mediated by CMLD011580 in the triple-hit lymphoma cell line, SC-1." (PMID 30718665, 2019). "Dual Bcl‐2 and Bcl‐XL inhibition with ABT263 (navitoclax) has shown single‐agent activity in a variety of leukaemias and lymphomas." (PMID 30537101, 2019).
lymphoma (continued). "In the 2016 WHO classification, this category has been eliminated and replaced by the category “high-grade B cell lymphoma, with MYC and BCL-2 and/or BCL-6 rearrangements”, which encompasses “double” and “triple-hit” lymphomas." (PMID 31115699, 2019). "Recently, there is growing interest in the double expressor lymphomas (DELs), defined as co-expression of 2 oncogenes (MYC and BCL2) based on immunohistochemical staining." (PMID 31702637, 2019). "Although EZH2, MYC, BCL2 and BCL6 are important prognostic biomarkers for lymphomas, our study shows that they poorly influence the sensitivity of lymphoma cell lines to DZNep-mediated apoptosis." (PMID 31419226, 2019). "BH3 mimetics such as the BCL-2/BCL-XL inhibitor ABT-737, its orally bioavailable derivative ABT-263/navitoclax, or BCL-2-specific ABT-199/venetoclax, have shown an ability to restrain lymphomagenesis in Eμ-Myc mouse models of lymphoma." (PMID 30728358, 2019). "Our findings suggest that the high-grade lymphoma with MYC and BCL2 translocations evolved through transformation of the FL by a process that entailed acquisition of the MYC translocation." (PMID 29793519, 2018). "So far, there have been various lymphoma cell lines that appear to have both MYC and BCL2 rearrangements." (PMID 30323893, 2018). "The BCL2-selective small-molecule inhibitors, S55746 and venetoclax (ABT-199), demonstrated a similar activity in 26 lymphoma cell lines." (PMID 30404918, 2018). "Whilst targeting Bcl-2 with inhibitors such as ABT-263 and ABT-199 has shown promise in lymphoid cancers, there has also been emergence of resistance to these therapies." (PMID 29899843, 2018). "We found that BCL2 and IRF4 are highly expressed in both Δ3C virus-infected, and WT virus-infected lymphomas, even though EBNA3C stabilizes IRF4 protein in vitro." (PMID 30125329, 2018). "Stem/progenitor cell lymphomas also dominated in Eμ‐BCL2/Eμ‐MYC DT, Eμ‐Bclx/Eμ‐MYC DT and Vav‐Mcl1/Eμ‐MYC DT mice 29, 31, 32, while Vav‐BCL2/Eμ‐MYC DT mice developed IgM−CD19+CD43+ pro‐B cell tumours." (PMID 29498802, 2018). "“Double-hit” lymphoma (DHL) represents a subset of B-cell malignancies characterized by the presence of MYC (8q24) rearrangement and concurrent BCL2 (18q21) or BCL6 (3q27) rearrangements." (PMID 30323893, 2018). "These therapies are RNA-based (not miRNA-based); they do not knockdown or overexpress miRNAs but target oncogenes such as Bcl-2 (NCT00285103) in CLL, STAT3 (NCT01563302) in DLBCL and lymphoma, and MYC (NCT02314052) in HCC." (PMID 30443251, 2018). "The first developed compound ABT-737, targeting BCL-2, BCL-XL and BCL-W, exhibited single-agent antitumor activity in preclinical models of lymphoma and small-cell lung cancer (SCLC), as well as in primary patient-derived CLL samples." (PMID 29570632, 2018). "Ours is the first reported case of composite lymphoma that includes elements of FL, CLL/SLL and high-grade B-cell lymphoma with MYC and BCL2 rearrangements." (PMID 29793519, 2018). "“Double-hit” lymphoma (DHL) is a high-grade B-cell lymphoma that harbors concurrent MYC and BCL2 or BCL6 rearrangements." (PMID 30323893, 2018). "An association between higher Bcl2 expression and sensitivity to Bcl2 inhibition has previously been described in both SCLC and lymphoma models." (PMID 29088717, 2017). "A worse outcome than double-expressor lymphomas show high grade B‐cell lymphomas (HGBL) with rearrangements of MYC and BCL2 and/or BCL6, the so-called double-hit or triple-hit lymphomas, which constitute a single category in the updated WHO classification." (PMID 29250206, 2017). "These “double-hit” or “triple-hit” lymphomas are included in the updated WHO classification in the category of high-grade B‐cell lymphoma (HGBL), with rearrangements of MYC and BCL2 and/or BCL6." (PMID 29250206, 2017).
lymphoma (continued). "The large B-cell lymphomas with c-MYC and either BCL2 or BCL6 rearrangements are subsequently termed double-hit lymphomas (DHL), while those with all three rearrangements are referred to as triple-hit lymphomas (THL)." (PMID 28379189, 2017). "The CD19 negative DLBCL were characterized further for other B cell lineage and lymphoma markers including CD20, PAX5, CD138, BCL2, BCL6, BCL10 and MUM1 using immunohistochemistry." (PMID 28484276, 2017). "The combination of MYC translocation with translocations of BCL2 and BCL6 can also occur, defining the triple-hit lymphomas (THL)." (PMID 28061782, 2017). "These lymphomas belong to the new category called “High grade B cell lymphoma (HGBL), with rearrangements of MYC and BCL2 and/or BCL6”." (PMID 28375188, 2017). "Rearrangements or translocations of both BCL-2 and MYC are hallmarks of “double-hit” lymphomas which are typically more resistant to R-CHOP and portent poor prognosis." (PMID 28191314, 2017). "Microscopic findings showed that the tumor was a hepatic MALT lymphoma, and immunohistochemical analysis revealed that the lymphoma cells were CD20+, CD79a+, BCL-2+, CD3−, and CD5−." (PMID 28353562, 2017). "This category was called “double hit” lymphoma (DHL) or triple hit lymphoma and now is recognized as “high grade B-cell lymphoma (HGBL) with rearrangements of Myc and Bcl2 and/or Bcl6." (PMID 28147336, 2017). "Both RLS (increased expression of bcl-2) and RLS-40 (overexpression of mdr1a/mdr1b genes) lymphosarcoma cells showing different types of drug resistance were less susceptible to the virus than KB-3-1 and B-16 cells." (PMID 27538520, 2016). "On the other hand, we identified CDK6 and BCL2 as JQ1 targets for transcriptional silencing in SCLC cells, as in leukemia, lymphoma and neuroblastoma." (PMID 27764802, 2016). "Many cancer cells, including leukemia, lymphoma and lung cancer cells, are addicted to IP3R/Bcl-2-complex formation for their survival, since tools that disrupt this complex trigger cell death." (PMID 27494888, 2016). "MYC translocation was present in four of 26 (15%) evaluable cases, two of them had an additional BCL2 rearrangement (Double hit lymphoma) and one patient had additional BCL2 and BCL6 rearrangements (Triple hit lymphoma)." (PMID 27285986, 2016). "“Double-expresser” lymphomas are defined based on IHC stains with MYC and BCL2 staining in more than a specified proportion of tumor cells." (PMID 27606052, 2016). "The aggressive nature of double-hit and triple-hit lymphomas is likely due to the concurrent rearrangement of both the pro-proliferative c-MYC oncogene and the anti-apoptotic BCL2 oncogene." (PMID 26654227, 2015). "Results also highlight the potential utility of a signature involving Bcl-2 overexpression, Rac1 activation and STAT3 phosphorylation for stratifying clinical lymphomas based on disease severity and chemoresistance." (PMID 26430964, 2015). "For example, bcl2 is an antiapoptotic factor upregulated by the EBV protein LMP1 during latency; ccl3 is a chemokine typically upregulated in lymphomas; and ccr7 is one of the first EBV-induced chemokine receptors documented." (PMID 26121143, 2015). "A proportion (21–83%) of DLBCLs with MYC translocation also harbour a BCL2 and/or BCL6 translocation, known as ‘double‐hit’ or ‘triple‐hit’ lymphoma." (PMID 27347428, 2015). "Most DH lymphomas had MYC and BCL2 gene translocations, whereas a small subset has MYC/BCL6 rearrangements." (PMID 26416427, 2015).
lymphoma (continued). "Importantly, we compared the prognostic differences of double CNA with classic DHL and protein double expression (MYC and BCL2/BCL6 coexpression) lymphoma (DEL) and indicated the special value of double CNA which might be an important supplement to the DHL system." (PMID 26158410, 2015). "One hundred seventy-two cases (84 %) were classified as MYC−, 17 (8 %) were MYC+/BCL2−/BCL6−, and 16 (8 %) were double/triple-hit lymphomas (i.e. MYC+/BCL2+, MYC+/BCL6+ or MYC+/BCL2+/BCL6+)." (PMID 26146524, 2015). "It was reported that MYC concurrent with BCL2 or/and BCL6 translocations in DLBCL, called double-hit lymphoma or triple-hit lymphoma (DHL/THL), determines highly aggressive clinical behavior with extremely poor outcome and resistance to chemotherapy." (PMID 26158410, 2015). "The term ‘double‐hit’ lymphoma was originally used to describe aggressive DLBCL with MYC and BCL2 translocation, then subsequently extended to include those with MYC and BCL6 translocation." (PMID 27347428, 2015). "Our results can be applied to many other types of cancers such as lymphoma, breast, colon, and gastric cancers, where FAK and/or BCL-XL/BCL-2 are overexpressed." (PMID 24523919, 2014). "We therefore determined the role of BCL-2 on autophagy in BCL-2+ and BCL-2− cell lines and human primary lymphoma samples." (PMID 25362242, 2014). "Immunophenotypically, these lymphomas often have a germinal center B-cell phenotype with positivity for CD10 and bcl6, and are frequently bcl2 positive." (PMID 25274079, 2014). "Recently, Abbott Laboratories developed a new Bcl-2-specific BH3 mimetic, ABT-199, which was shown to be efficacious against aggressive Myc-driven murine lymphomas with significantly reduced adverse side effects." (PMID 25314317, 2014). "Consistent with previous studies on lymphomas, we identified REL and BCL11A located at 2p16.1, and BCL2 at 18q21.3 being among the genes, whose expression was linked with copy number gains." (PMID 24625556, 2014). "Concurrent BCL2 and MYC rearrangements were found in four cases comprising two extranodal (gastric and brain) and two nodal lymphomas." (PMID 24887414, 2014). "ABT-737 and ABT-263 are highly specific for BCL-2, BCL-xL, and BCL-w and have proven efficacy on BCL-2/BCL-xL-dependent tumors such as leukemia and lymphoma." (PMID 25621172, 2014). "The lymphoma cells in the 12 primary hepatic DLBCL cases were positive for the following antigens (number of positive cases, % of total): CD10 (4, 33.3%), Bcl2 (6, 50%), Bcl6 (5, 41.7%), MUM1 (5, 41.7%), and CD25 (5, 41.7%)." (PMID 22395482, 2012). "Recently, a cell line was established from a patient with this complex lymphoma and analyzed using conventional tools revealing it contains both MYC and BCL2 translocation events." (PMID 23171647, 2012). "Accordingly, lymphomas with elevated Bcl-2 levels show lower proliferative capacities, suggesting that the impact of Bcl-2 on G0 to S phase transition is physiologically relevant and that high-grade gliomas may escape cell cycle block by downregulating Bcl-2 expression." (PMID 22431925, 2012). "The characteristic rearrangements of a DH lymphoma are the two chromosomal translocations involving MYC, BCL2 och IGH." (PMID 23171647, 2012). "Expression of Bcl2 and CD25 (IL2αR) was detected in the lymphoma cells of four of these eight DLBCL cases." (PMID 22395482, 2012). "In this work, we applied the siRNA targeted to the mRNAs of bcl-2, mdr1b, and mdr1a genes to overcome the MDR phenotype of lymphosarcomas RLS40 and RLS." (PMID 20470373, 2010).
lymphoma (continued). "Although blocking SFK activity inhibited the growth of a number of B lymphomas, some lymphomas such as SudHL-4, SudHL-6, OCI-Ly3 and OCI-Ly10 are more resistant due to an increased expression of the anti-apoptotic proteins Bcl-2 and Bcl-xL." (PMID 20043832, 2009). "Thus, interfering with Bcl-2 function is hypothesized to lead to apoptosis of lymphoma cells." (PMID 18275607, 2008). "We chose the U937 lymphoma cell line as the NKT-cell target because U937 cells express high levels of antiapoptotic Bcl-2." (PMID 17311012, 2007). "The BCL-2 gene, located at band 18q21, was rearranged in 42% of follicle centre lymphomas (FCL) and in 15% of diffuse large B-cell (DLBC) lymphomas." (PMID 9184180, 1997). "We hypothesized that the combination of enitociclib, venetoclax and prednisone (VVIP) would be active in R/R aggressive lymphomas, many of which express increased MYC, BCL2 and MCL1." (PMID 41169010, 2026). "If MYC protein levels exceed 40%, further investigation of MYC gene rearrangement is recommended to rule out transformation into high-grade lymphoma with BCL2 and MYC double rearrangement." (PMID 40881873, 2025). "In cases of DLBCL, immunohistochemical staining for BCL2 and c-MYC identifies “double expresser” lymphomas, a subgroup associated with a poor prognosis, though not as severe as double-hit lymphomas." (PMID 40428800, 2025). "A BCL-2 (B cell lymphoma 2) inhibitor venetoclax, in combination with CFI-400945 overcomes drug resistance and leads to a strong synergistic antitumor effect in lymphoma models." (PMID 41092110, 2025). "It highlights vital diagnostic tools, including CD45, B/T-cell markers, germinal center markers, and the Hans algorithm, as well as the role of FISH in identifying rearrangements of key genes MYC, BCL2, and BCL6, which are significant for recognizing double-hit and triple-hit lymphomas." (PMID 40428800, 2025). "A high proliferative index represented by Ki67 positivity favored a high-grade B-cell lymphoma with MYC, BCL2, and BCL6 rearrangement, possibly a double-expressor phenotype or a triple hit lymphoma if proven by classic cytogenetics, FISH, or other molecular or genetic tests." (PMID 40027040, 2025). "Our case exhibited BCL-2(-), CD10(+) germinal centers whereas the accompanying plasmacytic infiltrate was polytypic by immunohistochemistry for k and l light immunoglobin stains, thus excluding the possibility for these lymphomas." (PMID 40296965, 2025). "We can only speculate that hypoxia- and microenvironment-induced (over)expression of BCL-XL may be responsible for survival of venetoclax-resistant lymphoma clones, and conversely that co-targeting BCL-XL and BCL2 may prove synergistic in vivo." (PMID 39966387, 2025). "To mark candidate genes that became accessible to PU.1 by senescence-associated chromatin remodeling, we performed pathway annotation of transcripts that were positively regulated by PU.1 in TIS but not in non-senescent murine Eμ-myc;bcl2 lymphomas." (PMID 40159497, 2025). "Therefore, performing FISH for MYC, BCL2, and BCL6 rearrangements is essential to differentiate DH or TH lymphomas." (PMID 40428800, 2025). "The results showed negative MYC and BCL-2 gene rearrangements, thereby ruling out double-hit lymphoma." (PMID 41445799, 2025). "In addition to MYC gene translocations, lymphomas with BCL2 or BCL6 translocations and lymphomas with both MYC, BCL2, and BCL6 translocations are known as double-hit (DHL) or triple-hit (THL) lymphomas, respectively." (PMID 40729218, 2025). "Lymphomas with translocation of both MYC and BCL2, “double-hit lymphoma,” as well as cases with MYC and BCL2 co-expression, without underlying translocation, “double-expressing lymphoma,” have an adverse prognosis." (PMID 40721291, 2025).